TNF (tumor necrosis factor)
Diseases named in the same sentence as TNF in open-access papers (continued):
Sharing a sentence is not in itself a finding about the gene and the disease.
infection (continued). "While the mechanism by which SARS-CoV-2 infection downregulates ACE2 expression remains to be fully clarified, one of the proposed mechanisms for SARS-CoV-2 is through TNF-α; the infection induces the shedding of ACE2 via the upregulation of TNF-α-converting-enzyme (TACE)." (PMID 35163117, 2022). "Therefore, this cytokine mediates the inflammatory responses during infection with H. pylori as a result of the stimulating effect of H. pylori lipopolysaccharide on macrophages, leading to the synthesis of a great amount of TNF-α." (PMID 35884067, 2022). "Heightened levels of IL-6 and reduced TNF-α during infection may suggest a protective epithelial mechanism after injury." (PMID 35652591, 2022). "While clade V virus had fewer significantly differentially expressed genes, the major genes involved in cytokine storm; TNF pathway and neutrophil chemotaxis, Ccl2 and Ccl7 remained, suggesting similar, but milder presentation of pathology for its infection outcome." (PMID 36389747, 2022). "TNF is an essential cytokine for the host response to infection." (PMID 36203565, 2022). "Additionally, they found within the first 24 hours of infection, expression and secretion of inflammatory cytokines (TNF and IL-6) within the kidney and recruitment of neutrophils to the kidney are enhanced in C3aR−/− mice, compared to WT." (PMID 35925892, 2022). "However, in rat lungs, only TNF-α of Th1 cytokines was persistently increased during the late infection phase." (PMID 35617354, 2022). "Activated macrophages can inhibit lipoprotein lipase production to increase triglyceride levels by releasing TNF-α and IL-1 which may also be another factor that can promote the occurrence of infection." (PMID 36117592, 2022). "While an observational, post-marketing study indicates an increased risk of serious infections compared to non-biological treatment, recent meta-analyses have not found an increased risk of serious infections with anti-TNF treatment compared to placebo." (PMID 35140875, 2022). "However, cells challenged with ghB treated virions exhibited an upregulation in TNF-α expression (~0.31 log10)−2 h post infection." (PMID 35328462, 2022). "However, concerns regarding the increased risks of malignancy and severe infection following the use of biologics such as tumor necrosis factor-α (TNF-α) inhibitors still exist." (PMID 35116069, 2022). "Enrichment of the TNF pathway was found after infection with the cp strain." (PMID 35746747, 2022). "CTLs secrete cytokines, such as IFN-γ, TNF-α, and IL-2, after infection." (PMID 36389159, 2022). "Similarly, despite the ability of TLR2 to activate phagocytic activation of macrophages due to L. donovani infection, silencing either TLR2 or TLR3 impairs the secretion of NO and TNF‐α post‐infection of IFN‐γ‐primed macrophages with L. donovani promastigotes." (PMID 35119120, 2022). "The non-O- group showed the highest TNF-α-associated response, as well as a significantly less frequent response after 10 months post-infection." (PMID 34967260, 2022). "Besides, NO is one biomarker because during the pathogen’s infection process, the immune cells improved pro- IL-1β, TNF-α and INF-γ through promoting NO production." (PMID 36296333, 2022). "Moreover, during infection, there is an increase in proinflammatory cytokines (interleukin (IL)-1α, IL-1β, IL-6, IL-8, IL-18, tumor necrosis factor (TNF)-α, IFN-γ, leading to a disbalance in immune surveillance mechanisms and changes in the tissue environment." (PMID 36294658, 2022). "After infection of germ-line NR2F6-deficient mice with Listeria, CD8 CTLs enhanced antigen-specific immune memory cell formation and inflammatory cytokine secretion, such as IFN-γ, TNF-α, and IL-2." (PMID 36389159, 2022).
infection (continued). "In H1N1-infected cells, a higher expression of TNF-α mRNA was observed 2 h post-infection [ghA: (~2.4 log10); ghB: (~3.20 log10); ghC: (~2.82 log10)], with expression levels decreasing to a greater than control level at the 6 h time-point for ghA- (0.63 log10) or ghB- (~0.27 log10) treated samples." (PMID 35328462, 2022). "Indeed, the spike-specific CD8+ T cell pool in children at 6 months after primary infection was dominated by an IL-2−IFN-γ+TNF+ phenotype." (PMID 34937928, 2022). "In addition, increased expression of complement system components and elevated TNF-α levels promote exacerbation of infection." (PMID 35204727, 2022). "Additionally, the TNF-α/IL-10 ratio has been previously used as a biomarker for burn injury severity and infection." (PMID 35887586, 2022). "However, the expression levels of TNF-α gene were higher in response to the infections produced by A. dhakensis, followed by A. caviae and A. veronii (p < 0.05)." (PMID 35874671, 2022). "In addition, the use of systemic corticosteroids and TNF alpha inhibitors prior to infection was documented more frequently in moderate to critical infection." (PMID 36580495, 2022). "Furthermore, we have shown that TNFα is closely connected to many dysregulated proteins in the post-infection phase, although these results have to be interpreted with caution since TNFα regulates many functions also under healthy conditions." (PMID 36405747, 2022). "ILC1s, by producing IFN-γ and TNFα, may be involved in host defense against infections with viruses, bacteria, and protozoa including Toxoplasma gondii." (PMID 35163778, 2022). "On the other hand, anti-TNF alpha treatment may also be accompanied by serious side effects, such as infection, induction of autoinflammation and a potentially higher risk of malignancies." (PMID 35774100, 2022). "Additionally, ASFV-Δ9L/Δ7R infection exhibited dramatic induction of genes important during the acute-phase response, such as IL-1A, IL-1B, IL-10, and IL-18, tumor necrosis factor alpha (TNF-α), and several members of the complement pathway (C1R)." (PMID 35867564, 2022). "C. rodentium infection significantly increased the colonic expression of genes encoding for TNF-α and IL-6 at day four post infection compared to non-infected mice (p < 0.05)." (PMID 36266398, 2022). "This single-centre observational clinical pilot-study intended to investigate the role of selective biomarkers for inflammation and infection (PCT, ferritin, uB2MG, IL-6, IL-8, IL-10 and TNF-α) following TTPB and their association with post-operative complications such as infection and bleeding." (PMID 36154663, 2022). "We speculate that development of icDC1 and icDC2 during infection might provide a Tip-DC-like function in otherwise conventional DCs that might support T cell priming and TNF-α and nitric oxide generation." (PMID 36318581, 2022). "Of interest and in a similar way to Mφ, in vitro infection of PMNs with Brucella led to downregulated gene expression in key molecular pathways for PMNs physiology and function including phosphatidylinositol signaling, TNF signaling, and cellular senescence." (PMID 35979363, 2022). "IFN-γ and TNF-α are key cytokines involved in the anti-Listerial immunity and clearance of L. monocytogenes, and both cytokines are increased in SPexp mice early after the last infection with LCMV-Arm." (PMID 35878936, 2022). "TmTNF is able to maintain immune functions such as self-tolerance and resistance to infection while limiting other functions of TNF and may selectively inhibit solTNF/TNFR1 signaling." (PMID 36389810, 2022). "We aimed to explore whether the frequency of COVID-19 infection increased, the effect of comorbidities on the frequency of infection, and whether the severity of the disease and need for intensive care support increased in patients who used anti-TNF agents." (PMID 36161620, 2022).
infection (continued). "One retrospective cohort study has indicated no increased risk for serious infections compared to anti-TNF monotherapy, while another study demonstrated an increased risk." (PMID 35140875, 2022). "Cytokines such as IL‐1β, IL‐6 and TNF‐α are important in eliminating infection." (PMID 35502484, 2022). "Taken all together, our results showed that WBCATH reduced mycobacterium viability and induced the expression of the pro-inflammatory cytokine TNFα, related to Th1 immune response, which significantly contributed to controlling infections with drug-sensitive and drug-resistant Mtb." (PMID 36671276, 2022). "Notably, infection with Ado-LOXIN decreased the pattern of expression of TNF-α and IL-6 expression in liver parenchyma of HFD mice compared with ND mice and Ado-null." (PMID 35806336, 2022). "TNF-α is also important in the fight against infection and cancer." (PMID 36506032, 2022). "To verify this assumption, we performed an in vitro assay to stimulate N9 (mouse microglia cell line) with LSA, and the result confirmed that AC infection could induce microglia to secret TNF-α." (PMID 33683530, 2022). "TNF-α plays a role in cellular responses to infection and during immune responses." (PMID 35936727, 2022). "RT-PCR analysis showed that the levels of the inflammatory cytokines interleukin-1 (IL-1), interleukin-6 (IL-6), and tumor necrosis factor-alpha (TNF-α) in the heart on Day 5 post-infection were significantly lower in the hearts of KO mice than in those of WT mice." (PMID 35163412, 2022). "Finally, the TNF upstream regulator was activated in all experimental groups with the exception of 6-h infection with the H. pylori wt strain." (PMID 37193047, 2022). "However, IPA identified pro-inflammatory upstream regulators including PTGS2 (COX2), IL1A, and TNF that were activated after infection in aged mice." (PMID 35614490, 2022). "Among patients treated with biologics (28.6%), 6 individuals (33.3%) reported infections without any significant association with anti-TNF-α (p = 0.76)." (PMID 36079718, 2022). "Finally, the ileum cytokines IL-2, IL-12p70, IL-13, IL-17, GM-CSF, IFN-γ, TNF-α, and IL-33 remained unchanged relative to baseline over the course of infection in both genotypes." (PMID 35985797, 2022). "In-vitro and animal studies have shown that infection of neutrophils with Coxsackievirus B3, a prevalent enterovirus, triggers the release of tumor necrosis factor-alpha, interleukin-6, and other cytokines, which mediate inflammation and enhance neutrophil survival." (PMID 36337784, 2022). "Thus, we measured IFNβ, IL-6 and TNFα cytokine production at 24 hours post-infection in both female and male WT and Nlrx1-/- BMDMs infected with LgyLRV1+ parasites or stimulated with poly I:C." (PMID 35651602, 2022). "In addition, the infection induced an increase in interferon gamma (IFNγ) and tumor necrosis factor-alpha (TNF-α) in the intestine in the acute phase, in which this increase continued until the early chronic phase." (PMID 35069009, 2022). "In addition to IFN-γ and TNF, the pro-inflammatory cytokine IL-17A also appears to contribute to protective immune responses against infection with Mtb." (PMID 36139450, 2022). "However, M4N-treated Brucella-infected mice at 7 d post-infection displayed increased serum level of TNF-α and MCP-1 suggesting its potential use as a vaccine adjuvant." (PMID 36039381, 2022). "But, in RIP3-/- mice or in MLKL-/- mice, IL-17B had little infection to the plasma IL-6 and TNF-α." (PMID 36046722, 2022). "Moreover, TNF was significantly up-regulated during pathogen infection in the disk abalone’s (Haliotis discus discus) gill after 3 h, 12 h, and 24 h." (PMID 35606721, 2022). "Neuroinflammation (as a result of for instance infection) could be imitated in vitro by treatment with various concentrations of bacterial lipopolysaccharide (LPS), tumor necrosis factor α (TNFα), or Ureaplasma species." (PMID 35682683, 2022).
infection (continued). "A similar pattern was found in TNF-α mRNA levels after infection by the virulent H5N1 virus DK383." (PMID 36059479, 2022). "Pretreatment of cells with TNFα largely blocked the ability of HCMV to initiate infection in HFFs." (PMID 35834576, 2022). "This infection is generally characterized by inflammatory cytokines interleukin-1 beta (IL-1β), tumor necrotizing factor alpha (TNF-α), interleukin-6 (IL-6), chemokine (CX-C motif) ligand 2 (CXCL2), and IL-8 (also known as chemokine (CX-C motif) ligand 8-CXCL8)." (PMID 35053737, 2022). "NF-κB has long been considered a prototypical pro-inflammatory signalling pathway element leading to activation by pro-inflammatory cytokines, such as TNF-α, that represents an archetypal proinflammatory cytokine which is rapidly up-regulated upon either tissue injury and/or infection." (PMID 35629430, 2022). "The M1 response was higher during LdCen-/- infection, compared to WT L. donovani infection, and was characterized by the upregulation of inflammatory mediator transcripts (IL-1β, IL-12, TNF-α, and iNOS2) and the downregulation of M2-related genes (IL-10, YM1, Arg-1, and MRC-1 genes)." (PMID 35456106, 2022). "However, the patient had a history of frequent hospitalizations due to serious infections before using anti-TNF agents." (PMID 36422487, 2022). "However, TNF-α expression was detected in Delta infection, albeit later and milder than the previous variants, indicating that its regulation is independent from that of CCL4 and IL-6." (PMID 36073824, 2022). "In a study following children up to 47 months, there was no increased risk of malignancy or serious infection in children exposed to anti-TNF." (PMID 36225722, 2022). "These included cytokine–cytokine receptor interactions and viral interaction cytokine/cytokine receptor interactions related to the cytokine storm, immune, inflammation, and infection pathways such as TNF and JAK-STAT signaling pathways, and complement and coagulation cascades." (PMID 35177642, 2022). "During the acute phase of blood stage infection, the febrile response is a typical host immune defense triggered by pyrogenic cytokines, IL-6 and TNF-α, produced by circulating innate cells upon recognition by its pattern recognition receptors with pathogen-associated molecular patterns." (PMID 35677654, 2022). "to inhibit its induction, TNF-α appears to contribute to the control of systemic infection since its depletion prior to infection of mice with the B. abortus vaccine strain 19 exacerbated the early stage of infection." (PMID 35100011, 2022). "The increase in many signaling pathways related to the biosynthesis and actions of cytokines and chemokines, such as the cytokine−cytokine interaction pathway, TNF signaling pathway, and chemokine signaling pathway, was observed after the infection of Cajal cells and blood-nucleated cells." (PMID 35746747, 2022). "The pro-inflammatory cytokines IL-12p40 and TNF-α as well as the MC growth factor IL-3 were significantly increased in plasma of Mcpt4-/- mice compared to uninfected controls early after infection (4 days PI)." (PMID 35154114, 2022). "However, after 8 dpi, the cytokine concentrations of IFN-γ, TNF-α, and IL-1β in BCGΔRS01790 infection group were lower or similar compared with the other two infection groups at one or more time points." (PMID 35281073, 2022). "Furthermore, genes encoding pro‐inflammatory cytokines were upregulated on day 7 after infection, including TNF (TNF30), IL‐6 (IL‐631, 32) and VEGFA (VEGF‐A33) which have known functions in B‐T cell interactions or germinal centre development." (PMID 34169553, 2022). "Our hypothesis is that patients receiving anti-TNF-α therapy have more infections than patients receiving anti-integrin-α4β7 or conventional therapy." (PMID 35323234, 2022). "In addition to IFN-γ, TNF-α is an essential cytokine for the control of T. cruzi in the acute phase of experimental infection." (PMID 35097133, 2022).
infection (continued). "However, other pathways, such as phagocytosis and signal transduction, including tumor necrosis factor, mitogen-activated kinases and nuclear factor-κB, were only regulated after infection with BOS1FL1." (PMID 35163386, 2022). "A recent large population- based study reported a slightly increased rate of infections in anti-TNFα exposed infants, defined by hospital admissions for infection in the first year of life, as well as increased rates for antibiotic prescriptions in the second year of life." (PMID 36120653, 2022). "Increased NF-KB activation and TNF-α production induced by E protein during SARS-CoV-WT infection might be contributing to the observed miRNA-223 upregulation in WT versus SARS-CoV-ΔE-infected mice." (PMID 35229638, 2022). "We found higher concentrations of TNF-α and IL-6 in the acute phase of infection." (PMID 35456119, 2022). "It seems that a defect in TNF-α cytokine production resulted in uncontrolled infection." (PMID 36247511, 2022). "By the sixth day after infection, IL-6 and TNF-mRNA levels in the brain had increased by 300-fold." (PMID 35215199, 2022). "It is unclear whether anti-TNF-α de-escalation improves existing infections and/or skin abnormalities." (PMID 35625771, 2022). "When infection is present during pregnancy, inflammatory products—such as those associated with congenital infections and III—trigger microglial activation, resulting in neuroinflammation marked by the presence of IL-1β, TNF-α, and IL-6." (PMID 35844234, 2022). "Similarly, the overproduction of the proinflammatory cytokine tumor necrosis factor-α by immune cells that have recognized these superantigens results in suppression of phagocytic cell recruitment to the sites of infection." (PMID 35019696, 2022). "TNF-α is a pleiotropic cytokine produced by a variety of cells in response to infection or damage." (PMID 35168663, 2022). "Furthermore, TNF-α acts as both a recruitment and an activator factor for monocytes, macrophages and neutrophils by stimulating their migration to the infection site." (PMID 35884067, 2022). "For example, comparison of the lethal (P. yoelii XL) and non-lethal (P. yoelii XNL) strains of P. yoelii revealed that early production of TGF-β (within 24 h) in lethal infection is associated with delayed IFN-γ and TNF-α production, leading to uncontrolled parasite growth and 100% fatality." (PMID 36146602, 2022). "Furthermore, infection of human cells with L. braziliensis increased the production of TNFα and IL-10 in a TLR4-dependent manner, reinforcing the role of TLR4 as an important receptor in Leishmania infections." (PMID 35402314, 2022). "Furthermore, the production of high levels of TNF-α by microglia during the acute phase of the infection was found to play a role." (PMID 35615063, 2022). "After EVA71 infection, susceptible cells and nonspecific immune cells are stimulated first to produce cytokines such as TNF-α and IL-6." (PMID 36036059, 2022). "Notably, neutralization of TNF-α at an early, but not late, stage disease reproduced the results from TNFR1/2-/- mice, suggesting the importance of TNF signaling at the early stage of infection." (PMID 35479068, 2022). "Interestingly, we observed that the enhanced CD80+ CD86+ macrophages in colon tissues derived from mice with translocated infection were in line with the lower levels of secretion of TNF-α." (PMID 36445086, 2022). "This high risk of active TB in patients receiving TNF-α inhibitors is considered to be due to reactivation of LTBI rather than a new infection because most active TB cases develop within 3–4 months of TNF-α inhibitor initiation." (PMID 35330505, 2022). "Entry into the CNS may also be facilitated or enhanced as a consequence of inflammatory signals within the blood-brain barrier (i.e. TNF-α), as well as of infection of specific leukocyte populations." (PMID 35143571, 2022).